SNORD66 (small nucleolar RNA, C/D box 66)
Synonyms: HBII-142
Gene: Small nucleolar RNA gene on chromosome 3 (184,325,696 to 184,325,771, forward strand). Ensembl gene ENSG00000212158.
Gene Ontology:
Biological process: RNA processing
Cellular component: nucleolus
Homologues: Orthologues: chimpanzee SNORD66 (100% identical), macaque SNORD66 (99% identical), mouse Snord66 (88% identical), rat Snord66 (88% identical).
Diseases named in the same sentence as SNORD66 in open-access papers:
SNORD66 is named in the same sentence as 4 diseases in open-access papers, as found by Europe PMC text mining. Sharing a sentence is not in itself a finding about the gene and the disease. The quoted sentences say what the papers report.
lung cancer (5 papers, 2010 to 2017). A malignant neoplasm involving the lung. "Six snoRNAs (snoRD33, snoRD66, snoRA73B, snoRD76, snoRD78, and snoRA42) were identified whose changes were associated with lung cancer." (PMID 26246471, 2016). "SNORD66 was already suggested as a biomarker candidate for lung cancer due to its being up-regulated in the plasma of lung cancer patients." (PMID 28817650, 2017). "In the training set, a panel of two snoRNA biomarkers (snoRD66 and snoRD78) was developed, producing 74.58% sensitivity and 83.61% specificity for identifying lung cancer." (PMID 26246471, 2016). "SNORD33 is located in chromosome 19q13.3 that contain potential oncogenes in lung cancer, while SNORD66 and SNORD76 are situated in chromosomal regions 3q27.1 and 1q25.1, respectively." (PMID 20663213, 2010). "Moreover, snoRD33 is located at chromosome 19q13.3 that contains oncogenes involved in different malignances including lung cancer, whereas snoRD66 and snoRD76 are located at chromosomal regions 3q27.1 and 1q25.1, respectively." (PMID 22613733, 2012).
non-small cell lung carcinoma (2 papers, 2016 to 2023). A group of at least three distinct histological types of lung cancer, including non-small cell squamous cell carcinoma, adenocarcinoma, and large cell carcinoma. "The expression of SNORD33, SNORD66, and SNORD76 in the plasma is significantly enhanced in non-small cell lung cancer (NSCLC) compared with that in healthy individuals." (PMID 38003403, 2023).
cancer (3 papers, 2010 to 2019). A tumor composed of atypical neoplastic, often pleomorphic cells that invade other tissues. "Among the three cancer-associated genes, SNORD66 was also considerably overexpressed in plasma of COPD patients as compared with healthy controls (P < 0.01), implying that the cancer-associated gene whose changes were also related to COPD." (PMID 20663213, 2010). "In contrast, SNORD33, SNORD66, and SNORD76 exhibited significantly higher expressions in NSCLC patients as compared with healthy controls, suggesting that the elevated expressions of the three genes in plasma might be cancer-associated changes (All P < 0.01)." (PMID 20663213, 2010). "SnoRD33, snoRD66, and snoRD76 were found up-regulated in plasma from NSCLC patients, while snoRD33, snoRD66, snoRD42, and snoRD78 were investigated in sputum samples of patients with the same type of cancer." (PMID 31416190, 2019).
SNORD66 also shares sentences with these, for which no sentence is quoted: tumor (1 paper).